STAT3 (signal transducer and activator of transcription 3)
Diseases named in the same sentence as STAT3 in open-access papers (continued):
Sharing a sentence is not in itself a finding about the gene and the disease.
autoimmune disease (continued). "Aberrantly activated STAT3 is frequently observed in inflammatory diseases, cancer, and autoimmune disorders." (PMID 40005956, 2025). "Currently, further work is needed to clarify how STAT3 upregulates lncRNA expression and affects the differentiation of Th17 and other immune cells, mediating the development of autoimmune diseases." (PMID 38172648, 2024). "We previously investigated the SMILE-mediated regulation of AMPK and STAT3 in autoimmune diseases using animal models." (PMID 39533324, 2024). "STAT3 phosphorylation is essential for the development of Th17 cells, which are important drivers of a range of autoimmune diseases." (PMID 39359478, 2024). "Given this strong co-occurrence, we will herein discuss the role of STAT3 gene and its related pathway in T-LGLL, particularly in relationship to the conditions that sometimes associate with this leukemia such as autoimmune diseases." (PMID 38238319, 2024). "It is known that the STAT3 signaling pathway is closely related to the pathogenesis of inflammatory and autoimmune diseases." (PMID 38461326, 2024). "A transcription factor known as signal transducer and activator of transcription 3 (STAT3), which is known to be linked to autoimmune diseases, is also involved in the development of SLE." (PMID 38184662, 2024). "Patients with early‐onset multiorgan autoimmunity cased by STAT3 GOF variants exhibit clinical heterogeneity with incomplete penetrance and have overlapping features with other monogenic, multiorgan, autoimmune disorders." (PMID 38404237, 2024). "Golidocitinib is an orally available, potent and highly selective JAK (Janus kinase)-1 inhibitor of JAK/STAT3 signaling under clinical development for the treatment of cancer and autoimmune diseases." (PMID 37077916, 2023). "Studies have shown that the deletion of STAT3 in CD4+ T-cells protects mice against the development of experimental autoimmune diseases and suppresses the production of IL-17-expressing T cells." (PMID 37834058, 2023). "STAT3-related autoimmune disease is characterized by multiorgan autoimmunity, lymphoproliferative disease, and recurrent infections." (PMID 38020118, 2023). "S1PR1 is involved in autoimmune diseases by directly or indirectly acting on STAT3 to activate downstream signaling pathways." (PMID 37858140, 2023). "E26 transformation specific-1 (ETS-1), and signal transducer and activator of transcription 3 (STAT3) are transcription factors that have been confirmed as downstream targets of miR-125a-5p in autoimmune diseases." (PMID 37773129, 2023). "The Th17 cell subpopulation is known to be crucial in the development and pathogenesis of autoimmune diseases; STAT3 activation results in the expression of the RORγt transcription factor and the differentiation of Th17 cells." (PMID 37445800, 2023). "PDLIM2 suppresses Th1 and Th17 cell differentiation through inhibition of STAT3/4 and RelA in autoimmune disease, indicating that PDLIM2 plays a crucial role in T cell-mediated immune responses." (PMID 35707002, 2022). "Altered TLRs response and STAT3 activity in B cells are not only involved in immunodeficiency, but also autoimmune diseases." (PMID 35345674, 2022). "In this sense, miR-20b and miR-30a suppress Th17 differentiation in experimental autoimmune diseases by targeting RORγt and STAT3 and IL-21R, respectively." (PMID 35370692, 2022). "Pro-inflammatory cytokine IL-6 is instrumental in chronic inflammatory diseases and autoimmune diseases, as well as bone metabolism, and predominantly exerts its effect through the IL-6-signal transducer and activator of transcription 3 (STAT3) pathway." (PMID 36417596, 2022). "SARS-CoV-2 activated NF-κB and STAT3 through the AngI–AT1R pathway after SARS-CoV-2 infection, and then activated IL-6 amplifier (IL-6 Amp), which was a mechanism for STAT3 to overactivate NF-κB and led to various inflammations and autoimmune diseases." (PMID 34858386, 2021).
autoimmune disease (continued). "Although the benefit of reducing STAT3 phosphorylation at Y705 results in suppression of transcriptional activation of several cytokines in autoimmune diseases, this mechanism is also valid in treatment of cancer." (PMID 34531850, 2021). "Teffs from patients with autoimmune diseases, including MS, are resistant to Treg-mediated suppression, which is mediated by STAT3 signaling and further skews the functional balance of Teff:Treg toward Teffs." (PMID 33411696, 2021). "In this study, we have generated mice lacking STAT3 in CD19+ B cells (CD19-STAT3KO) and investigated intrinsic and extrinsic functions of STAT3 in B cells and its potential role in resistance or pathogenesis of organ-specific autoimmune diseases." (PMID 33004854, 2020). "STAT3 mediated resistance to these CNS autoimmune diseases derives from inability to produce Th17 cells and promotion of exaggerated expansion in Foxp3-, IL-10-, IL-4-, and IFN-γ-expressing T cells." (PMID 33004854, 2020). "On the other hand, the role of STAT3 in regulating CD19+ B-cell lineage commitment, most B cell effector functions, and its role in susceptibility or resistance to autoimmune diseases require further investigations." (PMID 33004854, 2020). "Regarding the different clinical presentations in STAT3 LOF and GOF mutation patients in our cohort, the latter had autoimmune disease, as mentioned in previous papers." (PMID 32944025, 2020). "This has led to the suggestion that STAT3 inhibitors can be used to suppress or modulate uveitis and other CNS autoimmune diseases mediated by Th17 cells." (PMID 33004854, 2020). "Multiple sclerosis and systemic lupus erythematosus are distinct autoimmune disease, but show certain similarities, including increased STAT3 expression and activation or increased SOCS3 expression." (PMID 33271810, 2020). "STAT3 is also known to play an important role in autoimmune diseases, including inflammatory bowel disease (IBD) and Mycobacterium tuberculosis infection." (PMID 33081347, 2020). "We generated mice with targeted deletion of Stat3 in CD19+ B cells (CD19-STAT3KO) to investigate intrinsic and extrinsic functions of STAT3 pathway in B cell development and during central nervous system (CNS) autoimmune disease." (PMID 33004854, 2020). "Herein, we briefly summarize our current knowledge of how STAT3 and STAT5 are implicated in inflammatory and autoinflammatory conditions as well as in autoimmune diseases." (PMID 31569642, 2019). "Zn has been shown to inhibit Th 17-mediated autoimmune diseases, partially inhibiting their development by impairing the activation of signal transducer and activator of transcription 3 (STAT3)." (PMID 31546724, 2019). "IL-23R deletion reduces Th17 cells and ameliorates autoimmune diseases in Act1−/− mice, implicating the importance of hyper Th17 cells (with increased STAT3 activation and IL-21 expression) for the autoimmune diseases associated with Act1 deficiency." (PMID 30013031, 2018). "It is well known that STAT3 plays a pivotal role in the differentiation of Th17 cells and is involved in the development of autoimmune diseases." (PMID 28332288, 2017). "Recently, metformin was shown to inhibit inflammation, and reduce the expression of IL-17 and p-STAT3 in experimental autoimmune disease mice." (PMID 26360050, 2015). "Inhibitors of p-STAT3 ameliorate experimental autoimmune diseases by promoting regulatory T (Treg) cell proliferation." (PMID 26360050, 2015). "As IL-6/STAT3 signalling blockers are successful in the treatment of chronic inflammatory or autoimmune diseases, their influence on PCa development needs to be carefully evaluated in future studies." (PMID 26198641, 2015). "Because STAT3 is a key transcription factor that is involved in Th17 differentiation, it is becoming a relevant treatment target for autoimmune diseases such as inflammatory bowel disease and RA." (PMID 24223854, 2013).
autoimmune disease (continued). "While this association has also been replicated in non-independent datasets, which included WTCCC data, the role of STAT3 in Crohn's and other autoimmune disease is well established." (PMID 23825936, 2013). "In line with their role in Th17 differentiation, STAT3 and RORγt are attractive targets for treating autoimmune diseases such as uveitis, multiple sclerosis and inflammatory bowel disease." (PMID 22238646, 2012). "Further experiments will have to elucidate the complex, and probably cell-type-specific antagonistic actions of the STAT3 transcription factor in the pathogenesis of this autoimmune disease." (PMID 22527947, 2012). "Previously, IL-17 has been reported to stimulate production of IL-6 and STAT3 activation in inflammatory cells and fibroblasts in an autoimmune disease, as well as in cancer cells." (PMID 22171994, 2011). "Among these, STAT3 (Signal Transducer and Activator of Transcription 3) and PTEN (Phosphatase and Tensin Homolog), which are significantly downregulated in patient esophageal mucosa, are implicated in eosinophilic gastroenteropathies and autoimmune diseases." (PMID 40243893, 2025). "STAT3 gain-of-function patients could atypically manifest very-early-onset autoimmune hypothyroidism as the first and only major autoimmune disorder." (PMID 41263296, 2025). "Zoledronic acid, previously shown to inhibit the JAK/STAT3 Pathway—a crucial axis in autoimmune diseases ‐may modulate immune responses relevant to vitiligo." (PMID 40856249, 2025). "STAT3 regulates numerous immune processes, involving granulocytes, NK cells, B cell antibody production and memory T cell development, and its dysregulation has been connected with various autoimmune diseases." (PMID 40607391, 2025). "High expression of nuclear/cytoplasmic STAT3 is observed in many patients with autoimmune diseases." (PMID 39825104, 2025). "Moreover, the strong correlation of p‐STAT3 expression with disease severity suggests that the immune alterations observed in MMD share similarities with those found in autoimmune diseases." (PMID 38566524, 2024). "STAT3 is a key regulatory factor for human Th17 cell differentiation, and abnormalities of its signaling pathway are key factors in chronic inflammation and autoimmune diseases." (PMID 38172648, 2024). "IL-6 signaling is mediated by the IL-6 receptor (IL-6R) and the signal transducer and activator of transcription 3 (STAT3), and dysregulation of this pathway has been implicated in the pathogenesis of several diseases, including cancer and autoimmune disorders." (PMID 37508437, 2023). "JAK/STAT3 pathway is critical for resistance to infection and maintenance of immune tolerance, and dysregulating this pathway may lead to autoimmune disease." (PMID 37771913, 2023). "Furthermore, it is noteworthy that STAT3 plays a critical role in the differentiation of TH17 helper T cells and is intricately linked to autoimmune diseases, recurrent infections, and other pathological conditions." (PMID 37833759, 2023). "Indeed, a synergy between NF-κB and STAT3 molecules based on pro-inflammatory cytokines (i.e., IL-6), which act as inflammation amplifier, was reported in several multiple inflammatory and autoimmune diseases and postulated also in COVID-19." (PMID 34518653, 2022). "Cytokines, responsible for the induction and maintenance of Th17 cells, stimulate signal transducer and activator of transcription 3 (STAT3), which is crucial in the differentiation of Th17 cells, which in turn are important in the immunopathology of RA and other autoimmune diseases." (PMID 35887269, 2022). "An extensive body of evidence links STAT3 with autoimmune diseases." (PMID 33557010, 2021). "Less is known about the contribution of STAT3-induced cell survival for autoimmune diseases and whether Bcl2 and inhibitor of apoptosis (IAP) family members play a role, as has been documented for cancer cells." (PMID 33557010, 2021).
autoimmune disease (continued). "Disease manifestations such as cytopenias and autoimmune diseases may result from the production of proinflammatory cytokines mediated by STAT3 hyperactivation, as well as from a direct attack on bone marrow by the STAT3-activated LGL." (PMID 34660312, 2021). "GRIM19 reduces STAT3 activation and ameliorates experimental autoimmune disease mediated by STAT3." (PMID 33467683, 2021). "Our results suggest that the increase in SOCS3 might have a role in the inactivation of STAT3 to suppress Th17 cell differentiation, aggravating autoimmune diseases such as EAE." (PMID 33205383, 2021). "In addition, we provide experimental evidence that expression of STAT3 in CD19 B cells confers protection from CNS autoimmune diseases as evidenced by exacerbation of uveitis in CD19-STAT3KO mice." (PMID 33004854, 2020). "Moreover, STAT3 is necessary for the differentiation of Th17 helper T cells, known as cells involved in a variety of autoimmune diseases including atopic dermatitis." (PMID 32566105, 2020). "In addition, plasma treatment in keratinocytes also suppressed STAT1 and STAT3 activation, which are involved in chronic allergic inflammation and autoimmune diseases, respectively." (PMID 31534179, 2019). "Here, we could identify that a nutritional affects IL-23-dominated autoimmune disease by influencing the HO-1/STAT3 axis." (PMID 28290522, 2017). "Notably, Socs3 supports differentiation of the Th17 and is implicated in autoimmune disease and a recent study reported that the expression of Th17 cell-mediated factors such as ROR-γt, and Stat3 increased significantly in diclofenac-treated mouse liver." (PMID 26934552, 2016). "Taken together, these results indicate that GITRL could promote Th17 cell differentiation by p38 MAPK and STAT3 signaling in autoimmune arthritis, which is considered a central pathogenesis of autoimmune disorders." (PMID 26657118, 2016). "The interference with STAT3 signalling could be a good therapeutic strategy to mitigate autoimmune diseases, including RA." (PMID 25767552, 2015). "Since STAT3 is a transcription factor that regulates a large number of proinflammatory cytokines, inhibition of STAT3 activation has been demonstrated as a promising target for several autoimmune diseases." (PMID 26360050, 2015). "Positive-feedback loop mediated by both NF-κB and STAT3 transcription factors may be important for the development of autoimmune diseases." (PMID 26501341, 2015). "Surprisingly, rather than the pro-inflammatory Stat3 activating cytokine IL-6 that drives Th17 cell differentiation, it was the anti-inflammatory cytokine IL-10 that promoted the Stat3 phosphorylation in Treg cells required for suppression of Th17-mediated autoimmune disease." (PMID 25076948, 2014). "STAT3 phosphorylation and IL-6 signaling are known to interfere with the delicate balance between Treg and Teff cells, a phenomenon often observed in autoimmune disease, supporting the pro-inflammatory potential of TL1A." (PMID 24416448, 2014). "GSPE may act as a therapeutic agent to treat immunologic diseases related with enhanced STAT3 activity such as metabolic disorders and autoimmune diseases." (PMID 24223854, 2013). "IL-6 can mediate autoimmune disease and tumour growth through the IL-6/STAT-3 signalling pathway." (PMID 22641338, 2012). "However, similar to STAT4, other IBD susceptibility genes such as IL23R, IL2/IL21, STAT3, and PTPN2 are associated with other autoimmune diseases." (PMID 20454450, 2010). "Largely intact ex vivo cytokine secretion in peripheral CD4+ naïve and memory T cells from patients with STAT3 GOF Syndrome presented here may also support the notion of tissue-specific disease pathogenesis versus broad systemic autoinflammatory/autoimmune disease." (PMID 39836489, 2025).
autoimmune disease (continued). "Clinically, JAK inhibitors (e.g., tofacitinib) already approved for autoimmune diseases show promise in preclinical models by reducing IL-6/STAT3-driven EMT, while TLR4 or NLRP3 inhibitors could blunt the initial DAMP-induced inflammatory cascade that seeds EMT." (PMID 41019090, 2025). "Thus, STAT3 SNPs have been associated with autoimmune thyroid diseases (AITD), STAT4 SNPs with early disease onset and severity of autoimmune diseases, including systemic lupus erythematosus and rheumatoid arthritis, STAT5A SNPs with atopic dermatitis and STAT6 SNPs with asthma." (PMID 38255152, 2023). "However, this notion does not preclude the involvement of STAT3 mutations in human autoimmune diseases." (PMID 30061896, 2018). "The authors suggest that Stat3 inhibition may provide a target for autoimmune diseases." (PMID 29056905, 2017). "In this context, under pathological conditions in which Th17 cells trigger an autoimmune disease, the dysregulated enhancement mediated by the amplifier may be induced by unchecked activation of NF-κB and/or STAT3 in fibroblasts via a variety of environmental and/or genetic factors." (PMID 26501341, 2015). "The most common manifestations of STAT3 GOF syndrome include lymphoproliferation, autoimmune cytopenia, enteropathy, and other autoimmune disorders." (PMID 41263296, 2025). "STAT3 governs the differentiation and effector function of CD8+ T cells throughout cancer and autoimmune diseases and has received widespread attention." (PMID 37771913, 2023). "All STAT family members (STAT1, STAT2, STAT3, STAT4, STAT5A, STAT5B, and STAT6) are related to autoimmune diseases." (PMID 35204186, 2022). "It has been shown that STAT3 binds to the promoter of JUNB to induce inflammation and promote the progression of autoimmune diseases." (PMID 34926700, 2021). "In other autoimmune diseases, tofacitinib was found to inhibit the phosphorylation of STAT1 and STAT3 in psoriatic arthritis FLS as compared to vehicle control." (PMID 31181818, 2019). "An advantage of this approach is that there is an already established arsenal of STAT3 and STAT5 inhibitors, which are currently under investigation for the treatment of cancer or autoimmune diseases, as reviewed in detail by Loh and colleagues." (PMID 31569642, 2019). "However, persistent activity of STAT3 in response to unregulated hormone signaling or oncogenic tyrosine kinases leads to the induction of genes that positively control proliferation in cancer, tumor cell invasion, or chronic inflammation that can progress into life-long autoimmune diseases." (PMID 21625522, 2011). "Viral infections may exacerbate SLE by activating STAT3, which promotes IFN-α secretion and Th17 cell differentiation by suppressing c-Maf expression, leading to Th17/Tregs imbalance and autoimmune disorders." (PMID 41383619, 2025). "To determine whether the suppression of IL-4 and IL-21 induced downstream pathways could serve as a strategy to treat autoimmune diseases, we used three JAK inhibitors to suppress IL-4/STAT6 and IL-21/STAT3 activation in anti-IgM-treated Ramos cells." (PMID 35911775, 2022). "Expansions of CD4+ LGL rarely manifest neutropenia or autoimmune diseases, but frequently co-occurred with solid tumors and often displayed STAT5B but not STAT3 mutations." (PMID 34359799, 2021). "STAT3 is also known to play a critical role in inflammatory bowel diseases (IBDs), with increased activation of STAT3 in some patients with active IBD as well as several autoimmune diseases." (PMID 31277507, 2019). "FOXP3, RORγt, STAT3, RelA/p65 (NF-κB), and c-Fos/c-Jun (AP-1) are transcription factors targeted by SIRT1, which are well-studied and are crucial to a balanced immune system, but the role of SIRT1 in autoimmune disease is only in the incipient stage, especially in the progression of SLE." (PMID 33981300, 2021).